TNF (tumor necrosis factor)
Diseases named in the same sentence as TNF in open-access papers (continued):
Sharing a sentence is not in itself a finding about the gene and the disease.
Hypocalciuria (1 paper, 2020). An abnormally decreased calcium concentration in the urine. "Proinflammatory cytokines, namely tumor necrosis factor-α, have been linked to the severity of hypocalciuria and low concentrations of vitamin D metabolites in critically ill patients." (PMID 33227914, 2020).
Hypocholesterolemia (1 paper, 2023). An decreased concentration of cholesterol in the blood. "A previous study showed that an increase in the levels of inflammatory cytokines, including interleukin-1 (IL-1) and tumor necrosis factor (TNF) can influence the metabolism of cholesterol and lead to hypocholesterolemia." (PMID 37464311, 2023).
hypogammaglobulinemia (1 paper, 2021). "Eight patients were noted to have developed hypogammaglobulinemia on follow-up while on anti-TNF treatment." (PMID 35095905, 2021).
idiopathic scoliosis (1 paper, 2015). A scoliosis with no known cause. "In conclusion, the observations of the present study indicated that high plasma levels of TNF-α in patients with adolescent idiopathic scoliosis at day 2 after surgery can predict the incidence of early POCD." (PMID 25780449, 2015).
idiopathic SRNS (1 paper, 2019). "Therefore, serum from idiopathic SRNS/FSGS patients activates the intrinsic podocyte TNFα pathway and this is unrelated to circulating TNFα levels." (PMID 31095586, 2019).
infectious encephalitis (1 paper, 2022). An acute infectious process that affects the brain tissue. "Subgroup-analysis for infectious encephalitis demonstrated no significant alteration in the concentration of the TNF-α (SMD, 10.91; 95% CI, -9.02–30.84; P = 0.28)." (PMID 36048783, 2022).
insulin-resistant diabetes (1 paper, 2016). "In hamsters with fructose feeding induced insulin-resistant diabetes, the serum levels of TNF-a and IL-6 were found to be significantly higher compared with those of the chow-fed hamsters." (PMID 27525022, 2016).
internalizing disorder (1 paper, 2022). A type of mental or behavioral disorder, typically in children and young adults, with symptoms including depression, anxiety and withdrawal. "Furthermore, there is mounting evidence of an association between childhood trauma and TNF-α, which may be a confounder in previous studies with pediatric internalizing disorders." (PMID 35880170, 2022). "Future research should aim for better sociodemographic, lifestyle, and clinical characterization of the pediatric sample to further understand the role of TNF-α in pediatric internalizing disorders." (PMID 35880170, 2022). "There is some evidence that TNF-α may play a role in mediating inflammatory activity in pediatric internalizing disorders." (PMID 35880170, 2022). "It has been speculated that TNF-α may be mediating the link between somatic depressive symptoms and treatment refraction in pediatric internalizing disorders." (PMID 35880170, 2022).
Intussusception (1 paper, 2020). An abnormality of the intestine in which part of the intestine invaginates (telescopes) into another part of the intestine. "Levels of serum cytokines on admission, including interleukin (IL) 2, IL-4, IL-6, tumor necrosis factor α (TFN-α), and interferon γ (IFN-γ) were rarely increased, except that 1 critically ill patient with underlying intussusception had an IL-6 level of 3868.86 pg/mL." (PMID 32492165, 2020).
ischemic colitis (1 paper, 2020). Inflammation of the colon due to colonic ischemia resulting from alterations in systemic circulation or local vasculature. "Induction of ischemic colitis increased TNF-α, IL-1β, and IL-6 expressions, whereas decreased adenosine A2A receptor expression (P < 0.05)." (PMID 32149087, 2020). "Expressions of inflammatory cytokines (TNF-α, IL-1β, and IL-6) and inflammatory mediator (COX-2) were upregulated in the ischemic colitis rats." (PMID 32149087, 2020). "Induction of ischemic colitis increased the expressions of inflammatory proteins, such as COX-2 (70–72 kDa), TNF-α (17 kDa), IL-1β (17 kDa), and IL-6 (22–27 kDa) in the colonic tissue (P < 0.05)." (PMID 32149087, 2020). "In the present study, treatment with PDRN effectively suppressed ischemic colitis-induced COX-2, TNF-α, IL-1β, and IL-6 expressions in the colonic tissues." (PMID 32149087, 2020). "In the case of PDRN + DMPX treatment, TNF-α, IL-1β, and IL-6 levels were not changed compared to ischemic colitis-induced group." (PMID 32149087, 2020).
juvenile ankylosing spondylitis (1 paper, 2012). "TNF-antagonists open new perspectives for treatment of juvenile spondylarthritis and, especially, juvenile ankylosing spondylitis since they have effected dramatic improvements also in patients with severe, and so far intractable, disease." (PMID 23095307, 2012).
keratinocyte carcinoma (1 paper, 2021). A skin cancer arising from the keratin-producing cells of the epidermis. "The pro-inflammatory cytokines IL-6, IL-8, and TNFα possess cancer-promoting functions and are commonly overexpressed in many malignancies including keratinocyte cancers." (PMID 35145494, 2021).
keratoacanthoma (1 paper, 2013). A dome-shaped, rapidly growing skin lesion composed of well differentiated squamous cells. "This may indicate that keratoacanthoma development is at least partly independent from TNF signaling." (PMID 23977171, 2013).
large cell carcinoma (1 paper, 2025). A malignant epithelial neoplasm composed of large, atypical cells. "Focal NED and amphicrine tumours exhibited cellular subpopulations enriched for KRAS, IL2-STAT5 and TNF signalling pathways, absent in small- and large-cell carcinomas, which were instead enriched for Myc and E2F pathways." (PMID 40705968, 2025).
limb ischemia (1 paper, 2017). A ischemia that involves the limb. "The significantly high levels of IL-6, TNF-α, MDA, and the increase of PMNs in lung tissues in group IR support the notion that the systemic inflammatory response and lipid peroxidation may be involved in mechanisms concerning pulmonary dysfunction after limb ischemia/reperfusion." (PMID 28629353, 2017).
lobular carcinoma (1 paper, 2021). "The TIMER database showed a negative correlation between the expressions of TNF-α and key regulators of mitochondrial OXPHOS complexes in basal breast vs lobular carcinoma." (PMID 33926547, 2021).
lower limb ulcers (1 paper, 2023). "We also showed that patients with diabetic foot, compared to diabetic patients without lower limb ulcers and healthy controls, have higher serum levels of inflammatory molecules, such as HIF-1alpha and VEGF, and comparable levels of IL-6, TNF-alpha and eNOS." (PMID 37365645, 2023).
lumbar spinal stenosis (1 paper, 2018). A spinal stenosis that involves the lumbar region of vertebral column. "Moreover, epidural treatment of the spinal nerve with an inhibitor of the pro-inflammatory cytokine TNF was reported to provide pain relief in patients experiencing radicular pain arising as a result of lumbar spinal stenosis." (PMID 30585203, 2018).
lymphangiectasia (1 paper, 2014). "g. tumor necrosis factor-α and interleukin-6) vascular or mucosal damage, and ruptured mucosal lacteals resulting in lymphangiectasia." (PMID 25490025, 2014).
Majeed syndrome (1 paper, 2021). Majeed syndrome is a rare genetic multisystemic disorder characterized by the triad of chronic recurrent multifocal osteomyelitis, congenital dyserythropoietic anemia, and variable transient inflammatory dermatosis. "Yet, only the cells from Majeed syndrome patients (versus NOMID or healthy controls) showed increased expression of osteoclastogenic mediators including IL-8, IL-6, TNF, CCL2, MIP1α, MIP-1β, CXCL8/IL-8 and CXCL1 in M2-like macrophages stimulated with LPS." (PMID 33670882, 2021). "Therapeutically blocking the IL-1RI or IL-1β (n = 10), but not TNF (n = 4), results in prompt resolution of systemic inflammation and healing of the sterile osteomyelitis seen in Majeed syndrome patients." (PMID 33670882, 2021).
malabsorption syndrome (1 paper, 2016). A syndrome resulting from the inadequate absorption of nutrients in the small intestine. "In UC the AA and GA genotype was associated with increased use of azathioprine and anti-TNF antibodies, but significantly less patients with the PTPN22 variant featured malabsorption syndrome (p = 0.026)." (PMID 27467733, 2016).
malakoplakia (1 paper, 2025). Malakoplakia is a chronic multisystem granulomatous inflammatory disease characterized by the presence of single or multiple soft plaques on various organs of the body. "Chronic intestinal inflammation and immunosuppressive therapies, such as tumor necrosis factor (TNF) inhibitors, may impair macrophage function and increase susceptibility to bacterial persistence and defective intracellular clearance, potentially predisposing patients to malakoplakia." (PMID 40568297, 2025).
malformations of the central nervous system (1 paper, 2024). "Furthermore, higher levels of CCL2/MCP-1 and TNFα expression have been observed in ZIKV-infected mothers who gave birth to infants with congenital malformations of the central nervous system than in pregnant women whose fetuses were normal." (PMID 38839691, 2024).
malignant mesothelioma (1 paper, 2019). A malignant neoplasm of the pleura or peritoneum, arising from mesothelial cells. "In malignant mesothelioma, ONC inhibits Tumor Necrosis Factor-alpha (TNFα)-elicited NF-κB nuclear translocation and reduces MMP9 activity, as well as cell invasiveness." (PMID 31783660, 2019).
Marfan syndrome (1 paper, 2017). A disorder of the connective tissue. "Inclusion of transforming growth factor-B1, implicated in thoracic aneurysms and Marfan syndrome, instead of TNF failed to coalesce the subnetworks." (PMID 27899403, 2017).
marginal zone lymphoma (1 paper, 2009). A usually indolent mature B-cell lymphoma, arising from the marginal zone of lymphoid tissues. "Specifically, we confirm that genetic variants in TNF/LTA (encoding for the proinflammatory cytokines TNF-α and LT-α) were most pronounced for DLBCL and marginal zone lymphoma." (PMID 19390683, 2009).
megacolon (1 paper, 2025). "Moreover, studies in human megacolon and megaesophagus have demonstrated a strong correlation between local inflammation, nitric oxide, IFN-γ, TNF-α, and neuronal destruction, which begins during the acute phase and progresses with chronicity." (PMID 41397009, 2025).
microphthalmia (1 paper, 2017). Congenital or developmental anomaly in which the eyeballs are abnormally small. "Interestingly, inflammation/TNF‐α‐dependent OTX2 downregulation might also have implications in congenital microphthalmia and auditory defects, common after intrauterine infections, notably with cytomegalovirus (CMV)." (PMID 27660103, 2017).
mild neurocognitive disorder (1 paper, 2024). "TNF‐α mRNA levels were significantly higher in the brains of Hispanics diagnosed with mild neurocognitive disorder (MND), compared to NCN controls (p < 0.05).Significantly higher levels of TNF‐α mRNA were found for the Hispanic group compared to the non‐Hispanic group (p < 0.01)." (PMID 38282400, 2024).
Mm (1 paper, 2019). "Although the effect of the HIF/COX/TNF axis in early Mm infection was negligible, this pathway is likely to have important roles in other disease situations." (PMID 31611882, 2019).
Mmm (1 paper, 2024). "We found that, when used at bactericidal concentrations, bovine complement efficiently abrogated the production of TNF by macrophages in response to Mmm infection." (PMID 38935768, 2024).
moderate heart failure (1 paper, 2021). Heart failure characterized by marked limitation in activity due to symptoms, even during less-than-ordinary activity, e.g. walking short distances (20b100 m). "The use of Etanercept, a TNF-α antagonist lowered the levels of biologically active TNF in patients with moderate heart failure." (PMID 33937353, 2021).
Moyamoya disease (1 paper, 2023). Moyamoya disease (MMD) is a rare intracranial arteriopathy involving progressive stenosis of the cerebral vasculature located at the base of the brain causing transient ischemic attacks or strokes. "IL-6 and TNF-α were associated with poor prognosis in adult patients with moyamoya disease." (PMID 36769472, 2023). "Multivariate stepwise regression analysis indicated that the G3 subgroup of IL-6 and the G4 subgroup of TNF-α were the independent risk factors for adverse prognosis in adults with moyamoya disease (OR 3.678, 95% CI [1.491, 9.074], p = 0.005; OR 2.996, 95% CI [1.180, 7.610], p = 0.021)." (PMID 36769472, 2023).
mucinous neoplasm (1 paper, 2025). "Similarly, TNF-α level was higher in the mucinous neoplasm group and it is thought that this group may be more related with inflammatory processes." (PMID 41451009, 2025).
mucormycosis (1 paper, 2022). "In mucormycosis, TNFα signaling may have a protective response, since patients treated with a tumor necrosis factor inhibitor have a higher risk of developing disseminated mucormycosis." (PMID 36520787, 2022). "In addition to the lack of knowledge about the immune response in the lung during pulmonary mucormycosis, our results suggest that an initial inflammatory response of AMΦ mediated by NO and TNF-α and/or H2O2 seems to be important for infection control." (PMID 36520787, 2022).
Multiple sulfatase deficiency (1 paper, 2016). "In mouse models of multiple sulfatase deficiency, sulfatide accumulation is associated with increased brain mRNA expression of TNF-a, IL-12 and MIP-1a17." (PMID 27079147, 2016).
myeloid sarcoma (1 paper, 2013). A tumor mass composed of myeloblasts or immature myeloid cells. "However, upregulation of TNFα was only prominent in miR-146a KO spleens that have developed myeloid sarcomas, but not in ones without overt tumors, suggesting that TNFα upregulation may be a quite late event in oncogenesis." (PMID 23705069, 2013).
myelolipomas (1 paper, 2010). "In patients with myelolipomas, the serum concentration of TNF α was lower, compared to control (2.06 ± 3.58 pg/mL vs. 12.09 ± 4.31 pg/mL; p < 0.05)." (PMID 20640152, 2010). "In subjects with myelolipomas, the serum concentration of TNF α was lower compared to the control." (PMID 20640152, 2010). "The low level of TNF α and high level of soluble forms of TNF α receptors in patients with myelolipoma may confirm the hypothesis that soluble forms of these receptors inactivate this molecule." (PMID 20640152, 2010).
myoma (1 paper, 2021). "It was emphasized that vitamin D can act as an inflammatory suppressant by diminishing the production of pro-inflammatory cytokines, including TNFα and IL6, in myoma." (PMID 34442017, 2021).
myopericytoma (1 paper, 2025). A usually slow growing, subcutaneous nodular neoplasm arising from myopericytes. "A growing body of work suggests that myopericytomas may share certain inflammatory or myofibroblastic pathways seen in conditions like DD, given the mutual expression of alpha-smooth muscle actin and involvement of inflammatory cytokines (TNF-α, IL-6)." (PMID 40507464, 2025).
myxoma (1 paper, 2012). A benign soft tissue neoplasm characterized by the presence of spindle and stellate cells, lobulated growth pattern, and myxoid stroma formation. "By comparison, as little as 2 μM chloroquine completely blocked IFN-α production and reduced TNF secretion by 55% in myxoma-infected pDCs." (PMID 22606294, 2012). "Strikingly, WT vaccinia infection blocks type I IFN/TNF induction in response to myxoma, TLR9 agonist CpG, or TLR7 agonist imiquimod." (PMID 22606294, 2012). "We found that Akt inhibitors VIII and X partially attenuated IFN-α and TNF production by myxoma-infected pDCs in a dose-dependent manner." (PMID 22606294, 2012). "Myxoma induction of IFN-α and TNF can be blocked by chloroquine, which inhibits endosomal acidification and maturation, and by inhibitors of cellular protein kinases PI3K and Akt." (PMID 22606294, 2012). "We found that treatment of myxoma-infected pDCs with 10 μM LY resulted in 97% inhibition of IFN-α secretion and a 75% decrement in TNF production." (PMID 22606294, 2012).
necrosis (1 paper, 2021). The phenotypic observation that death has occurred in groups of cells or in one or more tissues due to external factors, such as infection, toxins, mechanical trauma, loss of blood supply and other injuries (e.g. corrosion or burning). "A post-MI increase in TNF-α is also associated with LV systolic dysfunction, microvascular injury, and progressive myocardial necrosis." (PMID 34443591, 2021).
neonatal encephalopathy (1 paper, 2020). "Rapid increases in the levels of the main inflammatory cytokines TNF-α, IL-1β, and IL-6 under oxidative stress cause direct injury to the ischemic site and positively correlate with the severity of neonatal encephalopathy." (PMID 32074976, 2020).
Neonatal onset (1 paper, 2022). Onset of signs or symptoms of disease within the first 28 days of life. "Of interest, another MK2 inhibitor, ATI-450 (formerly CDD-450), showed inhibition of LPS-induced TNF for up to 4 weeks after dosing in a mouse model of neonatal-onset multisystem inflammatory disease (NOMID), whereas the global p38α inhibitor CDD-111 (also known as SD-0006) did not." (PMID 35982464, 2022).
neurofibromatosis (1 paper, 2023). A hereditary neoplastic syndrome in which tumors grow in the nervous system. "The mesenchymal subtype is strongly associated with a higher frequency of neurofibromatosis type 1 (NF1) mutations and upregulation of the tumor necrosis factor (TNF) and nuclear factor kappa-light-chain-enhancer of activated B cells (NF-κB)." (PMID 38067186, 2023).
neuroschistosomiasis (1 paper, 2024). Schistosomiasis of the brain, spinal cord, or meninges caused by infections with trematodes of the genus schistosoma (primarily schistosoma japonicum; schistosoma mansoni; and schistosoma haematobium in humans). "In the present study, the predominant production of TNFα over type 2 cytokines (IL-4 and IL-13) could suggest the domination of pro-inflammatory effects of TNFα during neuroschistosomiasis after 8 weeks post-infections." (PMID 39959586, 2024).
NK/T-cell lymphoma (1 paper, 2015). "The most common haplotype, CGGA (TNF-α-857 C > T, -308 G > A, -238 G > A, LTA +252 A > G) conferred a 1.5-fold risk of NK/T-cell lymphoma." (PMID 26108796, 2015). "Analysis of 12 single nucleotide polymorphisms (SNPs) in IL-10, TNF-α, lymphotoxin-α (LTA), and CTLA-4 genes was performed for 125 patients with NK/T-cell lymphoma and 300 healthy controls by PCR-ligase detection reactions." (PMID 26108796, 2015). "In this study, our results showed that LTA +252 A > G polymorphism is associated with a 2.9-fold risk of NK/T-cell lymphoma, but other polymorphisms of the IL-10, TNF-α, and CTLA-4 genes are not." (PMID 26108796, 2015).
obese syndrome (1 paper, 2023). "A positive correlation was observed between lipid hydroperoxide (LOOH) and levels of IL-15, TNFα, insulin, total cholesterol, LDL, and triglycerides in normal-weight obese syndrome patients." (PMID 38140309, 2023).
occlusive vascular diseases (1 paper, 2012). "Inflammatory cytokines, such as TNF-α, play a key role in the pathogenesis of occlusive vascular diseases." (PMID 22880111, 2012).
oesophageal stricture (1 paper, 2021). "IL-1β and TNF-α, two major pro-inflammatory cytokines that induce oesophageal stricture, were significantly suppressed by cell sheet engraftment." (PMID 34315989, 2021).
olecranon bursitis (1 paper, 2014). A bursitis that involves the olecranon. "There were two other published case reports of nonpulmonary M. kansasii infections (skin lesions and olecranon bursitis) in patients treated with anti-TNF-alpha agents." (PMID 25389506, 2014).
onchocerciasis (1 paper, 2024). Onchocerciasis is a form of filariasis, caused by the parasitic worm Onchocerca volvulus, transmitted by the black fly. "The results obtained from these different studies suggest the important roles of both TNF-α and IL-5 in the generation of protective immunity against onchocerciasis." (PMID 39432476, 2024).